FGF21 (fibroblast growth factor 21)
Description:
Stimulates glucose uptake in differentiated adipocytes via the induction of glucose transporter SLC2A1/GLUT1 expression (but not SLC2A4/GLUT4 expression). Activity requires the presence of KLB. Regulates systemic glucose homeostasis and insulin sensitivity.
Tractability: Antibody: its Gene Ontology location is reachable by antibodies, with high confidence; UniProt places it where antibodies can reach, with medium confidence; UniProt predicts a signal peptide or a membrane-spanning region.
Gene: Protein-coding gene on chromosome 19 (48,755,524 to 48,758,333, forward strand). Ensembl gene ENSG00000105550.
Subcellular location: Secreted
Pathways (Reactome):
Transport of small molecules: Assembly of active LPL and LIPC lipase complexes; Cellular hexose transport
Gene Ontology:
Molecular function: protein binding; fibroblast growth factor receptor binding; growth factor activity
Biological process: positive regulation of D-glucose import; positive regulation of ERK1 and ERK2 cascade; cell-cell signaling; fibroblast growth factor receptor signaling pathway; neurogenesis; positive regulation of cell population proliferation; positive regulation of cold-induced thermogenesis; positive regulation of MAPK cascade; regulation of cell migration; regulation of low-density lipoprotein particle clearance; signal transduction
Cellular component: cytoplasm; extracellular region
Genetic constraint (gnomAD): Loss-of-function variants: 14 observed, 14.44 expected, observed/expected ratio (o/e) 0.97, 90% interval 0.64 to 1.51. The upper end of that interval is the gene's LOEUF score, 1.51, which puts it in group 6 of 6, group 1 being the genes least tolerant of losing a copy. Missense variants: 281 observed, 264.91 expected, observed/expected ratio (o/e) 1.06, 90% interval 0.96 to 1.17. Synonymous variants: 113 observed, 119.45 expected, observed/expected ratio (o/e) 0.95, 90% interval 0.81 to 1.11.
Homologues: Orthologues: chimpanzee FGF21 (99% identical), macaque FGF21 (96% identical), dog FGF21 (85% identical), pig FGF21 (85% identical), guinea pig FGF21 (78% identical), rabbit FGF21 (77% identical), mouse Fgf21 (76% identical), rat Fgf21 (67% identical). Paralogues in human: FGF19 (33% identical), FGF23 (26% identical), FGF4 (25% identical), FGF5 (23% identical), FGF13 (23% identical), FGF16 (23% identical), FGF20 (23% identical), FGF6 (22% identical), FGF10 (22% identical), FGF9 (22% identical), FGF1 (22% identical), FGF22 (22% identical), and 9 more.
Diseases named in the same sentence as FGF21 in open-access papers:
FGF21 is named in the same sentence as 407 diseases in open-access papers, as found by Europe PMC text mining. Sharing a sentence is not in itself a finding about the gene and the disease. The quoted sentences say what the papers report.
Obesity (823 papers, 2010 to 2026). Accumulation of substantial excess body fat. "Given that FGF21 is recognised as a metabolic regulator, and elevated FGF21 levels are associated with obesity, we stratified our FGF21 data by BMI and age." (PMID 40551215, 2025). "For instance, mRNA encoding the hormone FGF21, which improves metabolic parameters in obesity and type 2 diabetes, has been successfully delivered in animal models, leading to reduced body weight and improved insulin sensitivity over weeks of treatment." (PMID 41438702, 2025). "The aim of the present study was to analyze the association between circulating concentrations of GDF15 and FGF21 in obesity and type 2 diabetes (T2D) in the context of aging." (PMID 40828431, 2025). "FGF21 is associated with metabolic conditions such as obesity, type 2 diabetes, and non-alcoholic fatty liver disease (NAFLD), where its levels are paradoxically elevated, possibly as a compensatory mechanism or due to resistance." (PMID 40806358, 2025). "Elevated FGF21 concentrations are commonly observed in metabolic disorders, including diabetes, insulin resistance, and obesity, and have been associated with increased mortality in conditions like coronary disease, chronic kidney disease, cancer, and sepsis." (PMID 40390366, 2025). "Mechanistically, hepatic Rab2A inhibition protected mice from high-fat diet–induced obesity and was associated with markedly elevated circulating FGF21, the phenotype largely rescued by adenovirus-mediated knockdown of either CREBH or APOB." (PMID 41314545, 2025). "In diet-induced obesity models, increased FGF21 expression appears to be associated with multiple factors, including organelle stress (such as endoplasmic reticulum and mitochondrial stress) and the phenomenon of FGF21 resistance." (PMID 41234361, 2025). "In clinical studies, elevated serum levels of FGF-21 have been associated with obesity, metabolic syndrome, and diabetes, which are components of MAFLD." (PMID 40430125, 2025). "Diseases such as obesity, type 2 diabetes, and nonalcoholic steatohepatitis (now called metabolic dysfunction-associated steatohepatitis) have been treated with FGF21 analogs, with promising results." (PMID 39884432, 2025). "Elevated GIP levels, particularly in obesity, are associated with increased hepatic fat accumulation, elevated markers of liver injury, and increased plasma levels of fibroblast growth factor 21 (FGF-21), a marker of metabolic stress." (PMID 41465555, 2025). "Early reports have evidenced changes in FGF-21 plasma/serum levels associated with obesity, T2DM, and MASLD." (PMID 41303424, 2025). "The in vivo activity of FGF21-164 was evaluated in leptin-deficient (ob/ob) and diet-induced obesity (DIO) mice." (PMID 40141314, 2025). "Firstly, we confirmed the obesity-associated up-regulation of FGF-21 expression in SAT, VAT, and the liver at baseline, but we also showed that SGLT2i treatment preferentially affects the expression of FGF-21 in lean more than in ob/ob mice." (PMID 40059147, 2025). "It has been found that FGF21 is associated with a variety of diseases related to glucose and lipid metabolism, such as obesity, fatty liver, coronary heart disease, atherosclerosis, myocardial infarction, etc." (PMID 40786047, 2025). "There is a clear correlation between increased serum levels of FGF21 and metabolic disease conditions such as diabetes, mitochondrial diseases, obesity, and aging, all of which have muscle loss as a common factor." (PMID 40675818, 2025). "In summary, the identification of FGF21 as a potential preoperative biomarker for weight loss offers a promising approach for optimizing treatment strategies in patients with obesity." (PMID 40377893, 2025).
Obesity (continued). ",111BACH1, has been linked to ferroptotic FGF21 secretion, a mechanism shown to mitigate obesity-related traits in mice." (PMID 40118008, 2025). "Paradoxically, obesity is associated with an increase in serum FGF21 levels and attributed to a reduction in FGFR and KLB expression on adipocytes." (PMID 39087083, 2024). "FGF21 is a peptide hormone known for its metabolic benefits, such as weight loss in obesity and improved hyperglycemia." (PMID 39872218, 2024). "High levels of circulating FGF21 are often linked to different dysfunctional metabolic processes, such as obesity." (PMID 38541057, 2024). "Noteworthy, in various metabolic disorders such as obesity, hyperlipidemia, diabetes, and metabolic dysfunction-associated steatotic liver disease, elevated serum FGF21 level were also recorded." (PMID 38983722, 2024). "This region, associated with macronutrient intake through genes like FGF21, suggests links between diet and chronic conditions such as obesity and diabetes." (PMID 39605717, 2024). "Although some clinical trials have suggested weight reduction after FGF21 analog treatment in subjects with obesity, type 2 diabetes, and fatty liver disease, the evidence for weight loss in subjects with obesity remains inconclusive." (PMID 39144082, 2024). "In a diet-induced obese mouse model, we show that repeated administration of DB-LNP encapsulating mRNA encoding human fibroblast growth factor 21 alleviates obesity and fatty liver." (PMID 38409275, 2024). "In contrast, A decrease in FGF21 concentrations in patients with obesity following weight loss achieved through diet and GS was observed, while no significant change was seen after RYGB." (PMID 39100807, 2024). "Despite our pooled analysis not identifying any clinical indices as an independent factor of DR incidence, previous studies have highlighted significant associations of obesity (BMI >30), high cholesterol levels, HbA1c, and FGF21 associated with DR incidence." (PMID 39687000, 2024). "In conclusion, a moderate low-protein diet, comprising 3–5% of total caloric intake, demonstrates the potential to enhance the transcriptional activity of Fgf21, leading to desirable anti-obesity outcomes, including significant weight loss." (PMID 38257122, 2024). "In conclusion, FGF-21 is involved in improving ectopic lipid deposition caused by obesity in the liver and skeletal muscles." (PMID 38732501, 2024). "Polymorphisms of the KLB gene are associated with obesity, further demonstrating the vital role of this receptor in facilitating FGF21 induced-weight loss." (PMID 39087083, 2024). "Fibroblast growth factor 21 (FGF21) positively regulates obesity-associated metabolic disorders and is elevated by KD." (PMID 38609395, 2024). "FGF21 is a hormone involved in the regulation of lipid and glucose metabolism and its expression is often associated with obesity and liver steatosis." (PMID 38541057, 2024). "Such a phenomenon is defined as FGF21 resistance, and it is considered that obesity is associated with resistance to FGF21." (PMID 39211324, 2024). "The increase in the concentrations of FGF21 serum causes type 2 diabetes and obesity, whereas a decrease in FGF21 serum concentration occurs in anorexia nervosa." (PMID 37189357, 2023). "Firstly, emerging solid evidence has demonstrated the beneficial role of FGF21 in preventing diet-induced obesity, weight loss, and improved glucose tolerance." (PMID 37009852, 2023). "In mouse models of obesity and type 2 diabetes, treatment with FGF21 improves glucose homeostasis and promotes weight loss." (PMID 37266540, 2023). "In this preliminary report, we aimed to assess baseline predictors of greater weight loss in patients with obesity undergoing a VLCKD focusing on the predictive role of FGF21." (PMID 36761216, 2023). "We also considered BMI as a possible confounder to control the possible effects of obesity on the association between serum FGF21 and sarcopenia." (PMID 37386374, 2023).
Obesity (continued). "The protective effects of FGF21 on preventing cardiac hypertrophy have been evaluated in pathological animal models such as uremic cardiomyopathy rats 81, obesity-associated cardiomyopathy mice 82, and hypertension mice." (PMID 36594101, 2023). "FGF21 and myostatin, myokine factors, are known to be associated with obesity and insulin resistance." (PMID 36981616, 2023). "FGF21 overexpression in mice resists diet-induced obesity, and FGF21 can affect weight loss, reduce plasma glucose and triglyceride levels, and boost insulin sensitivity in obese and diabetic vertebrate models without altering the calorie intake." (PMID 37108717, 2023). "Both GDF15 and FGF21 are central endocrine regulators of systemic energy metabolism and glucose homeostasis with robust therapeutical potential for the treatment of obesity and associated metabolic diseases." (PMID 37818094, 2023). "There is, indeed, evidence that protein requirements increase disproportionately relative to energy requirements with obesity and the metabolic syndrome and are associated with elevated FGF21." (PMID 37661737, 2023). "In the last years, FGF-21 has drawn attention for its putative beneficial role in obesity-associated metabolic complications." (PMID 37409233, 2023). "Previous studies reported FGF21 to be associated with age, obesity, and in NAFLD with the degree of steatosis." (PMID 37078380, 2023). "Overweight/obesity modified the association between asthma and 3 of the proteins: fibroblast growth factor 21 (FGF21), interleukin 4 (IL‐4), and urokinase‐type plasminogen activator (uPA)." (PMID 36973952, 2023). "Elevated serum FGF-21 is associated with metabolic disorders, such as obesity and diabetes mellitus, as well as with mitochondrial diseases." (PMID 36710345, 2023). "The association between FGF21 and obesity in humans seems more complex and controversial than that observed in primate and murine models." (PMID 36761216, 2023). "In the general population, FGF21 level has been confirmed to be closely associated with metabolic syndrome, including obesity, non-alcoholic fatty liver disease, HP, and diabetes." (PMID 37424900, 2023). "Similar results were observed in humans: the effects of LY2405319 (LY), a variant of FGF21 were tested in a randomized, placebo-controlled, double-blind trial in patients with obesity and T2D." (PMID 36923222, 2023). "Even though many aspects underlying the sex differences remain elusive, data suggest that hyperphagia of female UCP1-deficient mice blunts anti-obesity effects of FGF21 induced WAT browning." (PMID 37355753, 2023). "Variation in genetic loci involved in protein metabolism and signalling, including FGF21, would be expected to associate with variation in obesity risk, both between individuals within a population and between populations as a function of ancestral diet." (PMID 37661737, 2023). "QT interval prolongation has been associated with diabetes, obesity, and adiposity, cardiovascular diseases which are all related to an increased FGF21 level." (PMID 36180826, 2022). "Thereby, increased FGF21 concentrations in obesity were associated with a concomitant reduction in the FGF21 receptor complex." (PMID 36034917, 2022). "Novel FGF21 analogs are being studied as potential candidates in the treatment of obesity and liver-associated disease such as NASH." (PMID 35626717, 2022). "Recent studies have shown that increased circulating concentrations of fibroblast growth factor 21 (FGF21) are associated with obesity, metabolic disorder, and atherosclerosis." (PMID 35510201, 2022). "Previous studies showed that the elevation of circulating FGF21 was closely associated with metabolic disorders including obesity, diabetes and metabolic syndrome (MetS)." (PMID 36474191, 2022). "Paradoxically, there is a positive association between FGF21 levelsand a number of cardiovascular or metabolic diseases, such as coronary heartdisease, obesity and T2DM." (PMID 39077619, 2022).
Obesity (continued). "Obesity-induced insulin resistance results in abnormal elevated circulating insulin, promotion of fatty acid synthesis, and increase in FGF21 ultimately causing a FGF21-resistant state." (PMID 36499655, 2022). "In adiponectin-deficient mice, the effects of FGF21 including alleviation of obesity-associated insulin resistance, hyperglycemia, hyperlipidemia, and liver steatosis were reduced." (PMID 36618930, 2022). "Both stress-induced cytokines, GDF15 and FGF21, have attracted considerable interest as potential therapies for obesity and its associated metabolic disease." (PMID 36064109, 2022). "Acting via AMPK regulation, FGF21 protects against atrophy-induced inflammation, and its deficiency induces inflammation and worsens the obesity-induced atrophy of skeletal muscle." (PMID 35563026, 2022). "In agreement with the pharmacological data, genetic loss of function models of FGF21 aggravates obesity-induced and impairs the thermogenic response, possibly via increased hypothalamic inflammation." (PMID 36362103, 2022). "Due to its association with obesity and liver injury, the high levels of circulating FGF21 are often linked to different dysfunctional metabolic processes." (PMID 36140410, 2022). "Overweight and obesity were associated with a disturbance of the positive correlation between FGF21 and the stress biomarkers hair and time-integrated salivary cortisol concentrations, which were present in the control group." (PMID 35740758, 2022). "FGF21 can significantly improve carbohydrate and lipid homeostasis and promotes weight loss in animal models of obesity and diabetes." (PMID 36618930, 2022). "One working theory is that obesity-associated increases in FGF21 reflect an FGF21-resistant state due to observed downregulation of FGFR1c and KLB in the liver and WAT, as well as reduced efficacy of recombinant FGF21 (rFGF21) in mice and humans." (PMID 35046901, 2021). "In any case, the association of FGF21 with BMI and obesity appears to be paradoxical, since it has been demonstrated that FGF21 overexpression or administration prevents diet-induced obesity and insulin resistance." (PMID 33131010, 2021). "Because of its ability to regulate carbohydrate and lipid metabolism, FGF21 is considered to have multiple beneficial effects on major cardiovascular risk factors, such as hyperlipidemia, obesity, and diabetes." (PMID 34513950, 2021). "We investigated the association of serum FGF21 and genetic variants with aspects of food and drug craving and obesity related metabolic parameters including serum adipokine levels." (PMID 33805553, 2021). "Research on mice showed that PPARα modulated the methylation of liver Fgf21 and represents a form of epigenetic memory that persists from the postnatal period into adulthood that influence the risk of obesity in later life." (PMID 33670024, 2021). "Studies now have confirmed that methionine restriction promoted weight and fat loss and increased energy expenditure while increasing systemic FGF21 in mice with obesity, but also found that FGF21 was dispensable for the weight loss effects." (PMID 35046901, 2021). "In the seronegative group, FGF21 was only correlated with weight and waist circumference, showing an important association of FGF21 levels with the degree of obesity of the individuals." (PMID 34019585, 2021). "High serum FGF-21 levels were positively linked to metabolic diseases such as diabetes, obesity, mitochondrial disease, and aging." (PMID 34659937, 2021). "FGF21 is an important metabolic hormone whose expression can confer weight loss and improved metabolic function in various models of obesity." (PMID 34074713, 2021). "FGF-21 is a regulator of glucose and lipid metabolism with increased levels in obesity, which has been implicated in neuroendocrine control of female reproduction." (PMID 33764994, 2021).